ZNF804B (zinc finger protein 804B)
Synonyms: FLJ32110
Tractability: PROTAC: ubiquitination databases record sites on it.
Gene: Protein-coding gene on chromosome 7 (88,759,700 to 89,338,528, forward strand). Ensembl gene ENSG00000182348.
Pathways (Reactome):
Gene expression (Transcription): Generic Transcription Pathway
Gene Ontology:
Cellular component: nucleus
Genetic constraint (gnomAD): Loss-of-function variants: 78 observed, 104.58 expected, observed/expected ratio (o/e) 0.75, 90% interval 0.62 to 0.9. The upper end of that interval is the gene's LOEUF score, 0.9, which puts it in group 3 of 6, group 1 being the genes least tolerant of losing a copy. Missense variants: 1,671 observed, 1,641.8 expected, observed/expected ratio (o/e) 1.02, 90% interval 0.98 to 1.06. Synonymous variants: 622 observed, 591.51 expected, observed/expected ratio (o/e) 1.05, 90% interval 0.98 to 1.12.
Homologues: Orthologues: chimpanzee ZNF804B (98% identical), macaque ZNF804B (91% identical), pig ZNF804B (76% identical), dog ZNF804B (76% identical), rabbit ZNF804B (69% identical), mouse Zfp804b (68% identical), guinea pig ZNF804B (67% identical), rat Zfp804b (66% identical), tropical clawed frog znf804b (35% identical), zebrafish znf804b (6% identical). Paralogues in human: GPATCH8 (27% identical), ZNF804A (22% identical).
Diseases named in the same sentence as ZNF804B in open-access papers:
ZNF804B is named in the same sentence as 5 diseases in open-access papers, as found by Europe PMC text mining. Sharing a sentence is not in itself a finding about the gene and the disease. The quoted sentences say what the papers report.
autoimmune disease (1 paper, 2021). A disorder resulting from loss of function or tissue destruction of an organ or multiple organs, arising from humoral or cellular immune responses of the individual to their own tissue constituents. "In the ZNF804B locus, N-glycosylation of IgG, cytokines and proteases is also a regulatory mechanism in inflammation and autoimmunity associated with different autoimmune diseases." (PMID 34362956, 2021).
metabolic syndrome (1 paper, 2017). A cluster of metabolic risk factors for CARDIOVASCULAR DISEASES and TYPE 2 DIABETES MELLITUS. "In addition, single nucleotide polymorphisms in three genes (CROT, TSC1, RIN3) and at four loci (ANKK1, ZNF804B, CSRNP3, 17p11.2) were implicated as candidate determinants of obesity and metabolic syndrome, respectively." (PMID 28445147, 2017).
Obesity (1 paper, 2017). Accumulation of substantial excess body fat. "We also identified three genes (CROT, TSC1, RIN3) as new candidate susceptibility loci for obesity as well as three genes (ANKK1, ZNF804B, CSRNP3) and chromosome 17p11.2 as new candidate loci for MetS." (PMID 28445147, 2017).
ZNF804B also shares sentences with these, for which no sentence is quoted: Graves disease (1 paper); Intellectual disability (1).